NF1 (neurofibromin 1)
Diseases named in the same sentence as NF1 in open-access papers (continued):
Sharing a sentence is not in itself a finding about the gene and the disease.
demyelinating disease (2 papers, 2024 to 2025). A broad group of disorders that affect the myelin sheaths that cover the neurons. "It has been suggested that mutations in the NF1 gene might influence immune regulation or glial cell function, thereby increasing susceptibility to demyelinating diseases." (PMID 40951077, 2025). "Drugs that improve myelin function, including those that are currently in clinical trials for demyelinating diseases, could be repurposed to treat NF1 using schedules derived from fundamental research." (PMID 38339230, 2024).
developmental disabilities (2 papers, 2018 to 2022). "Irrespective of the neuro-developmental disabilities, we found the NF-1 group to complete EMPP measurements with a promising and equal success rate in comparison with the Non NF-1 subgroup." (PMID 36419654, 2022).
diffuse midline glioma (2 papers, 2022). A diffuse glioma that arises from the midline structures of the central nervous system. "For example, there is a higher incidence of neurofibromatosis 1 (NF1) mutations, unusual RAS mutations, and a larger population of H3K27M mutated tumors within this cohort, otherwise known as grade 4 diffuse midline glioma (DMG)." (PMID 36612169, 2022).
Dural ectasia (2 papers, 2024 to 2025). A widening or ballooning of the dural sac surrounding the spinal cord usually at the lumbosacral level. "Mesodermal dysplasia and dural ectasia, which are characteristic features of NF1 and KFS, may contribute to vertebral body defects which, in turn, may facilitate anterior meningeal herniation." (PMID 41226927, 2025). "While the association between dural ectasia in patients with Marfan syndrome and spinal anesthesia failure is well documented, similar occurrences in NF-1 have not been reported." (PMID 39352569, 2024). "A previous review of NF-1 found a 25.7% incidence of dural ectasia, suggesting that it is not a rare manifestation of NF-1." (PMID 39352569, 2024).
dysplasia (2 papers, 2011 to 2017). A usually neoplastic transformation of the cell, associated with altered architectural tissue patterns. "These mice do not develop tumours but recapitulate aspects of NF1 bone dysplasia, including deregulation of cartilage differentiation." (PMID 21726432, 2011).
emphysema (2 papers, 2021). "In this retrospective study, 71 patients with NF1 were evaluated for the presence of distinctive lung manifestations like reticulations, consolidations, type of emphysema, pulmonary nodules and cysts." (PMID 33446201, 2021). "Independent of the specific subtype of genetic mutation of the NF1 gene, a variety of different pulmonary pathologies may occur in NF1 patients, of which the major three findings were pulmonary cysts, intrapulmonary nodules, and paraseptal emphysema." (PMID 33446201, 2021). "However, we foundthat the prevalence of pulmonary emphysema was higher in the patients who weresmokers than in those who were nonsmokers (100% vs. 25%), which suggests thatemphysema cannot be attributed to NF1 alone; smoking status must be taken intoconsideration." (PMID 34866697, 2021). "Although pulmonary emphysema canbe seen in nonsmokers with NF1, there is insufficient evidence to conclude that itis due solely to NF1." (PMID 34866697, 2021).
Endocrine Neoplasia (2 papers, 2017 to 2025).
epilepsy syndrome (2 papers, 2015 to 2019). A syndrome that has a characteristic cluster of clinical features and/or lectroencephalographic (EEG) findings that reflect underlying epileptic activity. "As described, NF1 and TSC are two examples where mutations upstream of the mTOR pathway cause dysregulation and subsequent cellular alterations that correlate clinically with epilepsy syndromes and neurodevelopmental disorders." (PMID 26579319, 2015). "We report the case of a 15-year-old patient with TSC, NF1, and intractable epilepsy who only achieved seizure freedom with felbamate monotherapy and hypothesize a novel therapeutic approach to NMDAR-activated epilepsy syndromes." (PMID 26579319, 2015).
giant cell glioblastoma (2 papers, 2023 to 2024). "A patient with giant-cell glioblastoma benefited from procarbazine for a long period of time, then received combined therapy with bevacizumab and nivolumab, followed by targeted therapy with everolimus, due to the presence of NF1 mutation." (PMID 39684714, 2024). "In another patient with giant-cell glioblastoma and NF1 mutation, the use of everolimus (mTOR inhibitor) may have had an impact, but the patient died due to COVID-19 infection." (PMID 39684714, 2024).
glomerular disease (2 papers, 2021 to 2025). "Our case supports the emerging association between NF1 and glomerular disease." (PMID 40625468, 2025). "Given the rarity of significant glomerular disease in NF1, it is of clinical and scientific interest to understand any potential association, particularly if it is biologically plausible." (PMID 40625468, 2025). "A genetic link between NF-1 and IgAN or other glomerular diseases is not established." (PMID 34678898, 2021).
hereditary cancer (2 papers, 2019 to 2025). Malignant neoplasms occurring in families at a rate greater than that expected by chance and caused by germline mutations in a specific gene. "LP/P findings in pleiotropic genes linked to human development and hereditary cancer (TSC1, PHOX2B, WT1, SPRED1, NF1, LZTR1, HOXB13) were identified in several patients with syndromic phenotypes." (PMID 40060932, 2025).
Hypoglycemia (2 papers, 2023 to 2025). A decreased concentration of glucose in the blood. "There may be a combination etiology that make our patient has persistent hypoglycemia: NF‐1 and hypothyroidism." (PMID 37143466, 2023).
Infertility (2 papers, 2023 to 2025). "Reproductive phenotype was primarily observed in homozygous mutant mice except for Nf1, Rad51C, and Wt1, whereby heterozygous mutant males present the sub- or infertility." (PMID 40060932, 2025). "As infertility due to insufficient sperm motility and/or concentration may already necessitate IVF treatment, the higher percentage of sperm abnormalities found in the current PGT cohort of NF1-affected men may reflect a reduced threshold to add PGT to an already existing need for IVF." (PMID 37337089, 2023).
intracranial hypertension (2 papers, 2015 to 2019). A finding characterized by increased cerebrospinal fluid pressure within the skull. "We analyzed different clinical criteria that might influence the results: sex, age at diagnosis, NF1 associated with OPG, presence of DS or intracranial hypertension at diagnosis." (PMID 26098902, 2015). "Mild or moderate intracranial hypertension might be present in NF-1 patients regardless of having OPG." (PMID 31655505, 2019).
intraspinal tumors (2 papers, 2021 to 2022). "NF-1 may present multiple levels of involvement and is likely to form complicated paraspinal and/or intraspinal tumors." (PMID 34814912, 2021).
ischemia (2 papers, 2024 to 2025). A hypoperfusion of the BLOOD through an organ or tissue caused by a PATHOLOGIC CONSTRICTION or obstruction of its BLOOD VESSELS, or an absence of BLOOD CIRCULATION. "The pathological characteristics of arterial walls in NF-1 include ischemia due to the compression of the adventitia by fibroma cells, direct invasion of fibroma cells into the intima, and thinning of the intima due to smooth muscle proliferation." (PMID 40922847, 2025). "This phenomenon is a defining characteristic of ischemia in NF1." (PMID 39759687, 2024).
lobular breast carcinoma (2 papers, 2021 to 2022). "A recent specific retrospective study of 94 paired cases of lobular carcinoma demonstrated mutations in AKT1, ARID1A, ESR1, ERBB2, or NF1 only in 22% of patients with metastasis; PTEN and NF1 deletion and CYP19A1 amplification were seen in 19% of patients." (PMID 34771579, 2021).
lung fibrosis (2 papers, 2025). "Although NF-1 is congenital, pulmonary fibrosis and neurofibromatosis-associated diffuse lung disease (NF-DLD) are traditionally not evident before the patient reaches adulthood, typically appearing in the third or fourth decade of life." (PMID 41487738, 2025). "NF1-associated PH was most likely in this case as her sarcoidosis was not active and apart from some old apical fibrosis, she did not have significant lung fibrosis, traction bronchiectasis, multiple lung nodules, cysts, cavities, reticular changes or enlarged lymphadenopathy." (PMID 41523545, 2025).
Lymphoproliferative Disorder (2 papers, 2014 to 2017). "Since there is the lack of other similar published cases linking the presence of NF1 duplication with specific phenotypes, a comprehensive study about this type of mutation and its phenotype is warranted, mainly regarding the susceptibility to lymphoproliferative disorders." (PMID 25580325, 2014).
male infertility (2 papers, 2023 to 2025). The inability of the male to effect fertilization of an ovum after a specified period of unprotected intercourse. "Fertility assessments revealed a higher percentage of male infertility in males with NF1 compared to partners of affected females." (PMID 39860457, 2025). "Fertility assessment prior to IVF treatment showed a higher percentage of male infertility in males affected with NF1 compared to the partners of affected females." (PMID 37337089, 2023). "Also, we observed a non-significant increased rate of male infertility in men affected with NF1, knowledge which could aid couples in opting for adding PGT to an already indicated IVF treatment." (PMID 37337089, 2023).
metastatic cancer (2 papers, 2020 to 2025). A carcinoma which has spread from the original site of growth to another anatomic site. "Compared with normal tissue, NF1 mRNA expression was significantly reduced in primary BC tumors and further decreased in metastatic cancer (left)." (PMID 41155378, 2025). "Analysis of a few patients with metastatic cancer survive exceptionally longer than others under the same treatment identified multiple common mutations of NOTCH2, NF1, FANCD2, PIK3CB and EPHA5 in tumors that responded exceptionally well to treatments." (PMID 32600248, 2020).
mid-aortic syndrome (2 papers, 2015 to 2023). "Among RNF213 patients with MMD, patient 73577, a girl carrying the maternally inherited p.(Thr1705Lys) and p.(Leu1054Met) variants in cis, presented with mid-aortic syndrome, a rare form of aortic coarctation which has been recently linked to RNF213 as well as NF1 variants." (PMID 37012328, 2023).
mitral valve insufficiency (2 papers, 2022 to 2025). A mitral valve disorder characterized by incomplete valve closure. "Our study, conducted without presupposing NF1 PV types, confirmed an increased CHM risk (19%), with a trend toward increased PVS (7.7%), left heart obstruction (3.8%), and mitral valve prolapse/dysplasia (7.7%)." (PMID 40289159, 2025).
mucinous adenocarcinoma (2 papers, 2017 to 2024). An invasive adenocarcinoma composed of malignant glandular cells which contain intracytoplasmic mucin.
multiple myeloma (2 papers, 2018 to 2025). "Regardless of the mechanism, NGS findings suggest a clonal relationship with clonal evolution and a possible role of NF1, TNFAIP3 and TRAF3 in myeloid transformation of plasma cell myeloma." (PMID 29463311, 2018). "No family history of NF1 was present in the patient, except for her father, who passed away from multiple myeloma (MM)." (PMID 40708944, 2025).
non-melanoma skin carcinoma (2 papers, 2013 to 2024). "The increased risk of various types of carcinomas, including non-melanoma skin carcinoma, in patients with NF1 is recognized, however, the molecular mechanism of carcinoma development in patients with NF1 is not well understood." (PMID 24137429, 2013). "A 56-year-old female with an established diagnosis of NF1 and a history of melanoma in situ and nonmelanoma skin cancer presented with a rapidly growing pigmentary lesion in her right postauricular region." (PMID 39687068, 2024).
oligodendroglioma (2 papers, 2022 to 2025). A well-differentiated (WHO grade II), diffusely infiltrating neuroglial tumor, typically located in the cerebral hemispheres. "In contrast NF1 was found to be retained in primary lesions (9/9) and in 20/20 reference cases of conventional oligodendroglioma." (PMID 34967922, 2022).
optic atrophy (2 papers, 2019 to 2025). A disorder characterized by loss of optic nerve fibers. "Optic atrophy was noticed in a five-year-old boy with a NF1 pathogenic variant." (PMID 31717729, 2019).
osteomalacia (2 papers, 2014 to 2020). Disorder caused by an interruption of the mineralization of organic bone matrix leading to bone softening, bone pain, and weakness. "In diaphyseal cortical bone, the loss of Nf1 results in catastrophic deterioration of organic matrix quality and mineralization, resulting in local osteolysis/osteomalacia." (PMID 24465906, 2014).
ovarian serous carcinoma (2 papers, 2014 to 2017). "More than a third of all ovarian serous carcinomas (OSCs) harbour somatic NF1 mutations, identifying an alternative target for treatment and an additional prognostic marker." (PMID 28637487, 2017). "Alterations in NF1, including splicing mutations and homozygous deletions, were identified in 22% (9/41) of the primary ovarian serous carcinomas studied." (PMID 25026295, 2014). "Initial genome-wide screen of DNA copy number alterations (CNAs) identified apparent NF1 homozygous deletions in 2 out of 36 primary ovarian serous carcinomas." (PMID 25026295, 2014). "In the large scale integrated genomic analyses of 489 high grade serous ovarian carcinomas by the TCGA cooperative group, NF1 has been recognized as one of the most frequently altered genes, with aberrrations in 12% of the cases (8% homozygous deletions, 4% mutations)." (PMID 25026295, 2014).
parathyroid neoplasms (2 papers, 2015 to 2022). "NF1 mutations are most often associated with adrenal, gastroenteropancreatic, and parathyroid tumors." (PMID 36428741, 2022). "Also, there are several case reports in which NF1 was combined not only with the presence of parathyroid neoplasms, but also with other neoplastic disorders." (PMID 26442164, 2015).
paronychia (2 papers, 2022 to 2024). An acute or chronic infection of the soft tissues around the nail. "Selt and co-workers reported an occurrence of 7/18 (38.9%) of paronychia during the trametinib treatment among LGG patients with-or-without NF1." (PMID 36015104, 2022).
pilomyxoid astrocytoma (2 papers, 2019 to 2022). An astrocytic tumor of uncertain relation to pilocytic astrocytoma. "Good prognostic factors associated with OPG include younger age, NF-1 status, tumor location and extension, and histological diagnosis of pilomyxoid astrocytoma." (PMID 35586500, 2022). "There was 4.5% of patients with NF-1, 77.3% of the patients had OPG with hypothalamic extension; and 9.1% of the histological samples were pilomyxoid astrocytoma." (PMID 35586500, 2022).
pituitary tumor (2 papers, 2022 to 2025). A benign or malignant neoplasm affecting the pituitary gland. "We also review the available data for and against a causal association between NF1 defects and pituitary tumors." (PMID 39968302, 2025). "Only a few documented cases of NF1 and pituitary tumors with GH excess have been described, with no known co-existing hyperplasia, or loss of heterozygosity to NF1." (PMID 35456261, 2022). "One pituitary tumor from an adolescent patient who harbored a germline heterozygous p.Gln514Pro NF1 variant stained positive for GH and prolactin." (PMID 35456261, 2022). "In two previous case reports of patients with NF1 and GH excess, a pituitary tumor was reported as a serendipitous association." (PMID 35456261, 2022). "The lack of LOH for NF1 in the only pituitary tumor (patient 8) that we could test seems to argue against our hypothesis of a causal association between NF1 and pituitary tumorigenesis." (PMID 35456261, 2022). "We were only able to perform LOH studies for NF1 in one pituitary tumor (Patient 8), given poor quality or absence of DNA from other samples and/or patients." (PMID 35456261, 2022). "The pituitary tumor from patient 8 stained positive for reticulin, GH, prolactin (data not shown), and NF1." (PMID 35456261, 2022). "The pituitary tumor from patient 2 stained positive for NF1 and negative for GH (data not shown)." (PMID 35456261, 2022). "No LOH for NF1 was observed in patient 8′s pituitary tumor DNA." (PMID 35456261, 2022).
pulmonary hypertension (2 papers, 2023 to 2025). Increased pressure within the pulmonary circulation due to lung or heart disorder. "In recognition of its multifactorial pathogenesis, NF1 was classified under Group 5 PH at the 4th World Symposium on Pulmonary Hypertension in 2008." (PMID 41523545, 2025).
renovascular hypertension (2 papers, 2014 to 2023). High blood pressure secondary to renal artery stenosis. "Treatment modalities in renovascular hypertension secondary to NF1 involve a combination of drug therapy, PTRA, and surgery." (PMID 24678641, 2014).
retinal ischemia (2 papers, 2023 to 2024). A ischemic disease that involves the retina. "Second, she presented with atypical and rare findings of NF1, specifically vitreous hemorrhage due to retinal neovascularization preceded by retinal ischemia." (PMID 39759687, 2024). "In the ocular district, retinal ischemia secondary to Moyamoya syndrome has been reported, limited to case series, in patients with NF1." (PMID 37686284, 2023).
sleep disorder (2 papers, 2019 to 2025). A change from the patient's baseline sleeping pattern, in the hours slept and/or an alteration/dysfunction in the stages of sleep. "For this reason, studies on the association between sleep disorders and NF1 have reason to continue in order to clarify the underlying causes and to plan possible targeted treatments." (PMID 40299482, 2025). "This study laid the foundation for molecular research to explain a correlation between sleep disorders and NF1." (PMID 40299482, 2025). "Future studies employing multivariable regression models could better quantify the independent relationship between NF1 and sleep disorders." (PMID 40299482, 2025).